IL10 (interleukin 10)
Diseases named in the same sentence as IL10 in open-access papers (continued):
Sharing a sentence is not in itself a finding about the gene and the disease.
graft versus host disease (30 papers, 2009 to 2025). An immune system disorder that occurs after allogeneic hematopoietic stem cell transplant and is a reaction of donor immune cells against host tissues. "It has been demonstrated that the lowest incidence of severe acute graft versus host disease (GVHD) and remission is associated with homozygosity for the IL-10 haplotype, possibly due to the overproduction of IL-10." (PMID 26035439, 2015). "In line with our findings, a previous study showed that LAG3-KO CD4+ T cells secrete significantly more IFN-γ and IL-10 than WT CD4+ T cells in murine graft-versus-host disease." (PMID 37172058, 2023). "IL-10 reveals powerful immunostimulatory properties in vivo as well: infusion of exogenous IL-10 in mice recipients of fully allogeneic donor grafts leads to increased graft rejection and graft-versus-host-disease (GVHD)-induced mortality." (PMID 37359549, 2023). "MSCs can not only directly restrain proliferation of the effector B cells but also induce differentiation of the CD19+CD5+ B cell subset of patients with graft versus host disease, which secretes IL-10, thus being recognized as Bregs." (PMID 34790240, 2021). "Previously, others had described a suppressor T-cell population that secreted IL-10 and protected patients against graft-versus-host disease (GvHD)." (PMID 34335585, 2021). "Overexpressing IL-10 in MSCs suppressed the development of graft-versus-host disease, and MSCs overexpressing TNFR2 treat CIA in mouse more effectively than controls." (PMID 30079066, 2018). "CD101 is expressed on CD4+ and CD8+ T-cells, dendritic cells and monocytes, and appears to alter CD4+/CD25+/FOXP3+ T regulatory cell (Treg) function based on both a murine graft-versus-host disease model, and through IL10 secretion from human dendritic cells." (PMID 29108000, 2017). "Enhanced Treg production following IUT, particularly of CD62L+ CD25+ FOXP3+ Tregs, protects against graft-v-host disease, and together with putative Breg (expressing IL10, IL5, IL6, FOXP3, TGF-β), probably influenced the resulting tolerogenic or immunogenic responses." (PMID 37226255, 2023). "Despite the lack of CD146hi MSC-mediated activation of peritoneal macrophages to release the suppressive factor IL-10 in vitro, their administration in animals with graft-versus-host disease alleviates inflammation and leads to 40% survival rate up to 7 weeks post-transplantation." (PMID 35892560, 2022). "IL-10-DLI were infused in 12 patients with the goal of improving immune reconstitution after haplo-HSCT without increasing the risk of graft-versus-host-disease (GvHD)." (PMID 24550909, 2014). "This could be explained by the high levels of IL-10 secreted by these DCs and is coherent with data from the literature showing that MC significantly reduced inflammatory reactions in graft-versus-host disease and in infections, by an IL-10-dependent mechanism." (PMID 26834749, 2016). "In contrast, the CD8 CD45RClow T cells have the capacity to recognize alloantigens, but produce anti-inflammatory cytokines, in particular IL-10, a key cytokine that controls graft rejection and graft versus host disease (GvHD)." (PMID 23894540, 2013). "For example, ILC2s producing IL-10 (ILC210), have demonstrated robust immunomodulatory functions in the context of graft-versus-host disease (GVHD)." (PMID 40963622, 2025). "But VIP can act directly on the Teff cells – culture of CD25−Foxp3− Teff with VIP induces their differentiation into CD25+Foxp3+ Treg that express high levels of IL-10 and CTLA4 and are protective in a mouse model of graft versus host disease (GVHD)." (PMID 24550907, 2014). "Infused cells did not cause graft versus host disease (GvHD) and showed a high IFN-γ to IL-10 ratio, indicating Th1 priming in the first three weeks after infusion." (PMID 30558125, 2018).
graft versus host disease (continued). "For instance, transitional Breg from cord blood could be of benefit to mitigate chronic graft-versus-host disease after hematopoietic transplantation when using this source as opposed to bone marrow since these IL-10 B cells present a strong inhibitory capacity." (PMID 38077340, 2023).
liver cancer (30 papers, 2013 to 2025). An epithelial or non-epithelial malignant neoplasm that arises from the liver. "A recent study confirmed that increased serum IL-10 content in patients with liver cancer was associated with decreased DCs and phenotypic immaturity." (PMID 38381884, 2024). "The relationship between CD4+CD25+CD127LowTregs and TGF-β1 and IL-10 levels, and the analysis of the differences in immune status of patients with liver cancer are expected to provide valuable and diagnostic reference data for clinical treatment, the disease course, and prognosis of liver cancer." (PMID 32218692, 2020). "In liver cancer, specific cytokines such as Interleukin-12 (IL-12), Interleukin-10 (IL-10), and Interleukin-4 (IL-4) have been studied for their distinctive roles in modulating the tumour microenvironment." (PMID 40544399, 2025). "IL-10, another immunosuppressive cytokine, further contributes to the complexity of the immune landscape in liver cancer by inhibiting the synthesis of pro-inflammatory cytokines, thus reducing the effectiveness of the immune response against tumor cells." (PMID 39295859, 2024). "IL10 (interleukin 10) is an anti-inflammatory cytokine that exerts immunosuppressive effects in liver cancer." (PMID 39006665, 2024). "Beyond IL-10-expressing immunosuppressive B cells, in liver cancer, an FcγRIIlow/- Breg subset has been discovered, functioning as an inhibitory receptor to suppress the production of inflammatory cytokines in B cells." (PMID 39519376, 2024). "Murine tumors harbor IL-10-producing B cells analogous to those found in humans, such as the PD-1high B cell subsets identified in human liver cancer." (PMID 39519376, 2024). "At the same time, the content of IL-1α, IL-12 P70, TNF α, IL-1β and IL-6 was significantly reduced, and the content of IL-10 was significantly increased like in the previous liver cancer model." (PMID 34976592, 2022). "The levels of Treg cells and IL-2, IL-10, and TGFβ in the blood of patients with liver cancer were detected by flow cytometry and ELISA, respectively." (PMID 33204731, 2020). "The IL-10 concentration before treatment of primary liver cancer (577.49 ± 161.75 ng/L) was higher than that after treatment (480.43 ± 177.79 ng/L; P < 0.05)." (PMID 32218692, 2020). "Firstly, the microenvironment of liver cancer is always immunosuppressive, such as perfoming high concentration of IL-10 and TFG-β, which directly inhibit the activation of CAR-bearing cells." (PMID 32127929, 2020). "Compared with healthy people, Treg cells and IL-2, IL-10, and TGFβ contents in peripheral blood of liver cancer patients were increased." (PMID 33204731, 2020). "When the young miR‐15a/16−/− mice (8‐12 week) were transplanted with hepatic cancer cells, IL‐10‐producing CD19+ Tim‐1+ cells were significantly increased." (PMID 30467955, 2019). "In a liver cancer mouse model, MDSCs in the spleen, peripheral blood, lymph nodes, and tumor region secrete a large amount of IL-10, which suppresses the production of IL-12 by MDSCs and thereby suppresses the activation of T cells by MDSCs." (PMID 23717481, 2013). "In particular, macrophages express IL-10, TGF-β, and CD206, suggesting that they may act as cancer-associated M2 macrophages in liver cancer organoids." (PMID 38279326, 2024). "Therefore, elevated levels of these inflammatory markers (i.e. IL-1β, IL-4, IL-6, IL-10, TNF-α and C-reactive protein) increase the risk of liver cancer development." (PMID 37990536, 2023). "Bacteroides abundance↓,IL-10 levels↓,ameliorates unresectable liver cancer." (PMID 36817459, 2023). "Our previous studies had demonstrated that a high-dose (24.96g/kg/day) of JHD could delay the progression of liver cancer, and reduce the expression levels of IL-10 and TGF-β in tumor." (PMID 32140106, 2020).
liver cancer (continued). "Interestingly, the experimental rats with liver cancer induced by Diethylnitrosamine injection further confirmed the upregulation of miR-141 level, IL-10, and TNF-α and the disturbance in KLK10 and TNFSF-15 gene expression compared with their expression in normal rats." (PMID 38866875, 2024). "A large number of immunosuppressive cell types have been identified in liver cancer tissues, such as bone marrow–like inhibitory cells and regulatory T cells, which secrete TGF-β and interleukin 10 (IL-10)." (PMID 39028365, 2024). "For example, IgA+ Breg cells express PDL1, secrete IL-10 in TME and suppress local immune responses in several cancer types, such as human prostate and liver cancer." (PMID 36033455, 2022). "Before liver cancer treatment, the TGF-β1 and IL-10 concentrations were positively correlated with the percentage of CD4+CD25+ CD127lowTregs in patients with HCC respectively ((r = 0.526, P = 0.017; r = 0.546, P = 0.013)." (PMID 32218692, 2020). "After liver cancer treatment, the TGF-β1 and IL-10 concentrations were positively correlated with the percentage of CD4+CD25+ CD127lowTregs in patients with HCC respectively (r = 0.543, P = 0.013; r = 0.789, P=0.000)." (PMID 32218692, 2020). "The correlation between regulatory T cells and TGF-β1 and IL-10 has been widely reported, and the results of this study show that CD4+CD25+CD127low Tregs were positively correlated with TGF-β1 and IL-10 before and after treatment of liver cancer." (PMID 32218692, 2020). "Here, increased frequency of IL‐10‐producing CD19+ Tim‐1+ cells was seen in both aged miR‐15a/16−/− mice (15‐18 months) with the onset of B cell leukaemia and young knockout mice (8‐12 weeks) transplanted with hepatic cancer cells." (PMID 30467955, 2019). "In our results, we found that BMP2 signaling could enhance the expression of the Arg1 and IL6 in bone marrows, rather than iNOS, IL8, and IL10, indicating that BMP2 inducing MDSCs expansion might enhance liver cancer growth via IL6." (PMID 32195173, 2020).
septic shock (30 papers, 2006 to 2026). Shock caused by infection; frequently caused by gram negative bacteria, although some cases have been caused by other bacteria, viruses, fungi, and protozoa; characterized by fever, chills, tachycardia, tachypnea, and hypotension. "Plasma IL-10 also increases in patients with septic shock and is positively associated with inflammation severity and the development of multi-organ failure, likely due to IL-10 following pro-inflammatory cytokine responses." (PMID 41155249, 2025). "In patients with septic shock, calcitriol increased the expression of IL-10 and reduced IFN-α response." (PMID 40924491, 2025). "In septic shock patients, neutrophil counts, infection biomarkers (C-reactive protein, ferritin, and procalcitonin levels), and cytokines (IL-1β, IL-2R, IL-6, IL-8, IL-10, and TNF-α) increased significantly." (PMID 36845110, 2023). "BaP seems to dampen acute proinflammatory responses by suppressing proinflammatory cytokines (e.g., IL-1β) but induce anti-inflammatory cytokines (e.g., IL-10), and thus prevent septic shock." (PMID 37287978, 2023). "In patients with septic shock, decreased monocyte IL-10 production positively correlated with mHLA-DR and tumor necrosis factor-α production." (PMID 36552302, 2022). "Analysis of cytokine profiles following treatment revealed significant elevations in IL-6 and IL-10 in anti-HMGB1 pAb-treated mice 24 hours following surgery, which were both associated with survival in the septic shock patient cohort." (PMID 28724977, 2017). "IL-10 is an anti-inflammatory cytokine, which can modulate TNF-α production and it has been shown that IL-10 down-regulates TNF-α production in models of septic shock." (PMID 17201926, 2007). "In our case (septic shock), predictive enrichment basing solely on the supportive measurement (vasopressor requirement) was not sufficient and we needed to monitor the immune status (by the cytokines IFNγ and IL10)." (PMID 33767693, 2021). "We now show that the cAMP pathway directly upregulates IL-10 transcription and plays an important permissive and synergistic role in early, but not late, LPS-stimulated IL-10 mRNA and protein expression in mouse macrophages and in a mouse septic shock model." (PMID 31148944, 2019). "In humans with septic shock, the effect achieved with MT may be related to improving IL-10 levels." (PMID 38068931, 2023). "In clinical practice, KDSS is often misdiagnosed as septic shock, as both conditions present with peripheral circulatory dysfunction, hypotension, elevated CRP and increased interleukin‐10 (IL‐10)." (PMID 41055207, 2026). "We found that the plasma levels of IL-6, IL-8, IL-10, and MCP-1 were upregulated in all patients (all P value < 0.001), the septic group (all P value < 0.001), and the septic shock group (all P value < 0.001) compared with those in control groups." (PMID 36721090, 2023). "The septic shock group (n = 22) revealed a higher number of male subjects, CRP, IL-6, IL-8 and IL-10 levels, while lower TG, HDLc, monocyte numbers and M/H ratio at admission compared to the non-shock group (n = 27)." (PMID 36368184, 2022). "•Septic shock group showed lower TG, HDLc, monocytes and M/H ratio and higher CRP, IL-6, IL-8 and IL-10 levels at admission." (PMID 36368184, 2022). "In the LPS-induced murine septic shock model used in this study, the levels of IL-6, TNFα, MCP-1, and IL-10 increased 36 h after LPS administration, except IL-1β." (PMID 34066510, 2021). "A second serum module (BS3), which included IL6, IL8, IL10, IP10, GCSF, and MCP1, was elevated in patients with septic shock, ALI, and ECMO-death, in two independent cohorts." (PMID 29163498, 2017). "In patients with septic shock, calcitriol increased the expression of IL-10 (2.6-fold, adjusted P < 0.05), whereas in those without septic shock, calcitriol increased the expression of HMOX1 (1.3-fold, adjusted P < 0.05)." (PMID 40924491, 2025).
septic shock (continued). "In an experimental septic shock model, melatonin has been shown to counteract the rise in pro-inflammatory cytokine levels including IL-12, TNF-α, and interferon-γ, and to induce the production of the anti-inflammatory IL-10." (PMID 28895895, 2017). "In patients with septic shock, Monneret and colleagues described a significantly lower HLA-DR expression and higher IL-10 in non-survivors." (PMID 16899122, 2006). "The addition of either Day 1 IL-10 (AUC 0.725, 95% CI 0.628, 0.821) or TNF (AUC 0.722, 95% CI 0.625, 0.818) quartiles significantly improved the model; however, septic shock was no longer a significant predictor of persistence." (PMID 33820537, 2021). "However, in septic shock patients, the correlation between IFNγ and IL-12 (p70) with CETPI, IL-1β, TNF-α, IL-6, IL-8, and IL-10, were not significant." (PMID 36536294, 2022).
bladder cancer (29 papers, 2003 to 2024). "When data were stratified by types of cancer, we found that IL-10 −592C>A, −819C>T and −1082A>G polymorphisms were all significantly associated with the risk of bladder cancer in certain genetic models." (PMID 27995011, 2016). "Subgroup analyses by cancer types suggested there were significant associations between all the three investigated IL-10 polymorphisms and bladder cancer." (PMID 27995011, 2016). "Indeed, circulating cytokines in patient plasma such as interleukin-6 (IL-6), IL-8, and IL-10 were implicated in poor patient responses to ICBs in patients with kidney, breast, and bladder cancer and melanoma." (PMID 38259453, 2023). "Firstly, the number of studies investigating the associations of certain IL-10 polymorphisms with renal cancer or bladder cancer is still limited, and sample size of several included studies were obviously not sufficient, which precluded us from drawing definite conclusions." (PMID 27995011, 2016). "Indeed, patients with bladder cancer appear to develop a Th2 dominant status with a deficient-type immune response due to an increase in IL-10 levels." (PMID 23181118, 2012). "Besides, promoter region polymorphisms of IL-10 may serve as potential biological markers, especially for bladder cancer." (PMID 27995011, 2016). "Additionally, IL-10 −1082A>G polymorphism was also significantly associated with the risk of bladder cancer in AA versus GG (P = 0.02, OR 2.00, 95% CI 1.13–3.55), AG versus GG (P = 0.01, OR 2.03, 95% CI 1.16–3.55), and GG versus AA+AG (P = 0.009, OR 0.49, 95% CI 0.28–0.84)." (PMID 27995011, 2016). "Lentinan suppresses the progression of bladder cancer, accompanied by a significant reduction in IL-10 and TGF-β levels in MDSCs and Tregs." (PMID 39605905, 2024). "It has been demonstrated in co-culture experiments that IL-10 production by bladder cancer cells leads to increased PD-L1 expression on monocytes and downstream suppression of T cell immune responses." (PMID 31824850, 2019). "BCG also induced a strong release of IFN‐γ, TNF‐α, IL‐1β, IL‐10, and IL‐12p70 in human bladder cancer cells." (PMID 30358081, 2019). "Murine bladder cancer studies utilizing anti-IL-10 neutralizing antibody have shown similar results, with BCG treatment inducing an enhanced DTH response and increased bladder mononuclear infiltrate." (PMID 22778725, 2012). "Our observation in this experiment is consistent with a recent report showing that the circulatory levels of IL-4, IL-5, and IL-10 were significantly higher in bladder cancer patient serum than in normal samples." (PMID 22962576, 2012). "Several human tumors, including melanoma, non-small-cell lung carcinoma, renal cell carcinoma, and bladder cancer, have been found to express elevated levels of IL-10." (PMID 22778725, 2012). "The rationale of this approach is based on the fact that IL-6 and IL-10 are cytokines overexpressed in bladder carcinoma, and with a role in the interaction between cancer cells and the evironment." (PMID 23181118, 2012). "FOXP3-positive T cells and increased IL10 levels are present in human bladder cancers and in the mice models." (PMID 22013484, 2011). "Thus, LINC00702-activated DUSP1 suppresses bladder cancer cell proliferation and inhibits the secretion of inflammatory cytokines IL-4, IL-10, and TNF-α M2-OAM in bladder cancer." (PMID 38139370, 2023). "Some studies have suggested that blockade of IL-10 may improve the therapeutic efficacy of the BCG vaccine in the treatment of bladder cancer patients." (PMID 36080458, 2022). "Luo reported that blocking IL-10 can enhance the effect of BCG immunotherapy for bladder cancer." (PMID 33204728, 2020). "Several murine studies have demonstrated that after IL-10 knockout mice are inoculated with bladder cancer, they have an improved BCG and local immune response, increased bladder mononuclear infiltrate, enhanced DTH responses, greater antitumor activity, and prolonged survival." (PMID 22778725, 2012).